SENP6 (SUMO specific peptidase 6)
Diseases named in the same sentence as SENP6 in open-access papers (continued):
Sharing a sentence is not in itself a finding about the gene and the disease.
tumor (18 papers, 2010 to 2025). "The SUMO protease SENP6 is essential for the proliferation and survival of almost all known tumor cell lines." (PMID 36768878, 2023). "The transposon insertion pattern of Senp6 was characterized by scattered and bi-directional insertions, suggesting Senp6 as a tumor suppressor gene." (PMID 35022408, 2022). "Taken together, these data identify SENP6 as a functionally relevant tumor suppressor in murine and human BCL." (PMID 35022408, 2022). "We propose that the cohesin complex is one potential target of SENP6-mediated tumor suppression." (PMID 35022408, 2022). "To identify critical SENP6 targets that potentially mediate its tumor-suppressive role in BCL, we scrutinized two recent proteomics studies that defined SENP6 targets 23,25." (PMID 35022408, 2022).
cancer (12 papers, 2010 to 2025). A tumor composed of atypical neoplastic, often pleomorphic cells that invade other tissues. "This identifies SENP6 as a promising new target for the treatment of MMR-deficient cancers." (PMID 25302077, 2014). "With regard to MYC-dependent cancers, we found a strong SENP6-dependent increase of SUMO2/3 conjugates, revealing that SUMO conjugation is activated either by induction of the SUMO conjugation machinery or by loss of the cellular safeguard deSUMOylase SENP6." (PMID 35022408, 2022). "The results confirmed that SENP6 is a bona fide regulator of centromeric CENP-A levels both in cancer and primary cells." (PMID 31980633, 2020). "We also demonstrate that SENP6 depletion leads to a reduction in cell proliferation and mitotic problems that ultimately lead to cell death, implicating a clinical potential for a SENP6 inhibitor against highly proliferative cancer cells." (PMID 31485003, 2019). "Thus, this in vivo experiment proved that loss of Senp6 accelerated MYC-driven B-cell lymphomagenesis in mice, providing direct experimental evidence that deregulated SUMO deconjugation accelerates cancer formation." (PMID 35022408, 2022). "Importantly, 17 of these candidate SENP6-controlled proteins were also identified as putative cancer genes in our transposon screen." (PMID 35022408, 2022).
SENP6 also shares sentences with these, for which no sentence is quoted: infection (5 papers); Arthritis (2); cognitive decline (2); lung adenocarcinoma (2); melanoma (2); bladder tumor (1); Burkitt lymphoma (1); cataract (1); cerebral infarction (1); cognitive deficits (1); Eμ (1); fibrosis (1); head and neck squamous cell carcinoma (1); hippocampal atrophy (1); infarct (1); kidney damage (1); laminopathies (1); laryngeal carcinoma (1); lung carcinoma (1); malaria (1); neurological disorders (1); oral squamous cell carcinoma (1); penile cancer (1); prostate carcinoma (1).